ICAM1 (intercellular adhesion molecule 1)
Diseases named in the same sentence as ICAM1 in open-access papers (continued):
Sharing a sentence is not in itself a finding about the gene and the disease.
tumor (continued). "Intercellular adhesion molecule-1 (ICAM-1) is known to play an important role in the interaction between tumor cells and host cytotoxic effector cells." (PMID 26087182, 2015). "The binding of ICAM-1 to specific receptors increases the adhesion of inflammatory cells and tumor cells to endothelial cells, activates endothelial cells, and facilitates penetration into inflammatory tissue." (PMID 26368286, 2015). "The present study investigates the impact of celecoxib on tumor immune surveillance and the role of ICAM-1 within this process." (PMID 26513172, 2015). "ICAM-1 is required for cell adhesion and plays an important role in inflammation-induced tissue adhesion, tumor metastasis, and regulation of immune response." (PMID 26368286, 2015). "ICAM-1 deletion-mediated efferocytosis induces macrophage polarization toward the M2 phenotype, leading to promotion of tumor metastasis." (PMID 26068788, 2015). "Increased ICAM-1 levels have been correlated with CTLs binding to tumor cells and enhancing cytotoxicity." (PMID 26579226, 2015). "Third, the celecoxib-induced increase of LAK cell-mediated lysis of tumor cells was abrogated by neutralizing antibodies against ICAM-1 and LFA-1." (PMID 26513172, 2015). "The ICAM1 protein is dramatically induced by this mechanism and is critical for tumor growth in vivo, thus indicating a novel mechanism for adaptation to LCFA starvation and hypoxia as a means to promote tumor growth." (PMID 25879517, 2015). "Infiltration of tumor infiltrating lymphocytes was more frequently observed in the ICAM-1-positive tumors in this study." (PMID 26513172, 2015). "The mRNA levels of CD86 and ICAM-1 in tumor tissues collected at 14th day after HIFU treatment were significantly increased in the HIFU group." (PMID 26485753, 2015). "The present study provides first-time proof for celecoxib to induce upregulation of the adhesion molecule ICAM-1 on the surface of tumor cells, resulting in increased tumor cell lysis by LAK cells." (PMID 26513172, 2015). "In other murine models ICAM-1 overexpression on tumor cells was found to elicit a reduced tumor growth." (PMID 26513172, 2015). "The molecular adhesion of cancer cells to the vasculature is necessary for subsequent tumour intra-/extravasation and vascular ICAM-1 significantly increases adhesion and CCID formation." (PMID 26513020, 2015). "Incubation with silvestrol did not significantly alter the intensity of expression of class I MHC, nor did it have a significant impact on the expression of co-stimulatory molecules or ICAM-1 on tumor cells." (PMID 25393910, 2015). "ICAM-1 staining in DU145/sh-E2F1 tumor tissues was remarkably higher than that in DU145/sh-Con, consistent with the data obtained from Western blot assay." (PMID 24742333, 2014). "ICAM1 expression was highly upregulated upon combined IL-4 and TNFα treatment, which can support T cell/tumor interaction." (PMID 24885059, 2014). "It was observed that expression of ICAM-1 in DU145/sh-E2F1 tumors was higher than control and DU145/sh-ICAM-1 tumors, indicating that the increase in ICAM-1 expression is correlated to suppression of DU145 xenograft tumor growth by E2F1 knockdown." (PMID 24742333, 2014). "Specifically, cabozantinib treatment upregulated the expression of MHC-I molecules, ICAM-1, Fas, and calreticulin on tumor cells." (PMID 25388653, 2014). "It has been reported that murine LFA-1 on NK cells adheres to human ICAM-1 on tumor cells and provides an anti-tumor effect, and ICAM-1 plays an important role in cytolysis by NK cells." (PMID 24742333, 2014). "ADAM17 is involved in the cleavage of numerous surface molecules, most of which are considered to be relevant in tumour-associated processes such as cell growth, migration and invasion (TNF-α, CD44, L1-CAM, L-selectin, ICAM1, CX3CL1, etc.)." (PMID 25246708, 2014). "ICAM-1 supports metastasis by making it easier for ICAM-1-expressing tumor cells to separate from each other and invade surrounding tissue." (PMID 24743777, 2014).
tumor (continued). "The in vivo effect of E2F1 and ICAM-1 expression on DU145-derived tumor growth was evaluated in the xenograft mouse model." (PMID 24742333, 2014). "Egfl7 can promote tumor growth by repressing ICAM-1 and VCAM-1 expression, then limiting immune cell infiltration, as observed in breast and lung carcinoma murine models." (PMID 24734218, 2014). "Our studies support a model whereby for E2F1 regulation of tumor immune escape mediated by suppressing ICAM-1." (PMID 24742333, 2014). "This is supported by previous and current findings demonstrating increased expression of TAAs and other proteins contributing to efficient CTL lysis, such as MHC I and ICAM-1, following exposure of tumor cells to sublethal radiation." (PMID 24480782, 2014). "ICAM-1 has been shown to have higher levels in tumor tissues and antibody targeting of ICAM-1 induces potent macrophage-dependent antimyeloma activity." (PMID 24743777, 2014). "Previous murine studies have shown that the introduction of the ICAM-1 gene into tumor cells using retroviral vectors led to enhanced antitumor responses." (PMID 24742333, 2014). "Tumor infiltration of immune cells mediated by ICAM-1 was thought to be an attempt by the host organism to combat malignancy." (PMID 24742333, 2014). "In this study, we examined the intracellular signaling pathway involved in IL-6-induced ICAM-1 expression and tumor migration in human OSCC." (PMID 24398980, 2014). "Further, intracellular adhesion molecule-1 (ICAM-1) has been shown to enhance tumor cell proliferation and invasion and has been identified as being responsible for endothelial adhesion of cancer cells, thus strongly influencing metastatic potential." (PMID 25238234, 2014). "ICAM-1 is a representative adhesion molecule involved in the interaction among tumor cells, the endothelium, and ECM." (PMID 24901215, 2014). "It has been reported that MMP-9 cleaves ICAM-1 and participates in tumor cell resistance to natural killer cell-mediated cytotoxicity." (PMID 23803661, 2013). "Our IHC results present an upregulation of ICAM-1 in tumor tissue, along with the increasing of NF-κB, and suggested that the promotion effect of TET on NF-κB and ICAM-1 expressions is closely related to its antiangiogenesis effects." (PMID 23762115, 2013). "Overexpression of the endothelin-B receptor by tumor endothelial cells inhibits concurrent ICAM-1 expression, thereby impairing the ICAM-1/LFA-1-mediated transmigration of leukocytes." (PMID 23763830, 2013). "Taken together, these results indicate that WISP-1 and ICAM-1 expression correlates with tumor stage in patients with OSCC." (PMID 24205072, 2013). "More interestingly, the in vivo administration of ANT shRNA modulates the surface markers of cancer cells such as the MHC class I, Fas and ICAM-1; thus, it is an important molecule for inducing strong anti-tumor immunity." (PMID 23522027, 2013). "We found that the accumulation of tumor infiltrating CIK cells was correlated with the expression of ICAM-1 and VCAM-1." (PMID 23799045, 2013). "The accumulation of CIK cells was increased around the tumor vessels with high expressions of ICAM-1 and VCAM-1, indicating that CIK cells infiltration is related with endothelial cell adhesion molecules." (PMID 23799045, 2013). "Two days post-exposure to RFA sham or low-dose (30 s), medium-dose (60 s), or high-dose (90 s) RFA, excised CEA+ tumor cells were evaluated by flow cytometry for expression of ICAM-1, TRAIL-R2, MHC class I, Fas, and HSP70 proteins." (PMID 23894654, 2013). "On day 17, the phenotype of pooled excised CEA+ tumor cells was analyzed by flow cytometry for cell-surface expression of Fas, ICAM-1, H-2Kb, and H-2Db." (PMID 23894654, 2013). "The inhibitory effect of artesunate on the tumor of the mouse model as well as ICAM-1 and MMP-9 protein expressions were determined by Western blot." (PMID 24229621, 2013). "The adhesion molecule intercellular adhesion molecule-1 (ICAM-1) plays a critical role during tumor metastasis." (PMID 23803661, 2013).
tumor (continued). "In contrast, the high levels of ICAM1 expression and ROS production, which characterize these senescent mesothelial cells, enhanced the tumor cell adhesion." (PMID 23451255, 2013). "In the current study, we found that the high level of WISP-1 expression correlates strongly with ICAM-1 expression and tumor stage in OSCC patients." (PMID 24205072, 2013). "MMP-9 and ICAM-1 have been shown to be expressed in response to NF-κB activation, and are known to be major mediators of tumor cell invasion." (PMID 22768286, 2012). "It has been shown that CRC metastases are related to the ability of cancer cells to adhere to the microvascular endothelium of the lung that expresses the ligands for ICAM-1 on the tumor cell surface." (PMID 23098564, 2012). "Association of sunitinib with poxvirus vaccination encoding for B7-1, ICAM-1, LFA-3 and the CEA antigen promoted the enhancement of CEA-specific CD8+ T cells in the tumor." (PMID 23320019, 2012). "Vascular endothelial cells within tumor vessels respond to RT by upregulation of ICAM-1 and E-selectin and thereby facilitate leukocyte arrest and adhesion prior to transmigration." (PMID 23251903, 2012). "Granulocytes are attracted to the tumor site via expression of intercellular adhesion molecule-1 (ICAM-1)." (PMID 24213498, 2012). "Epigenetic agents can also induce (re)expression of a number of silenced genes encoding other immunoactive molecules, such as co-stimulatory molecules, adhesive ICAM-1 (CD54), NKG2D receptor and tumour-associated antigens." (PMID 22015556, 2011). "On the opposite, EphB4, FGFR1, Tie2, Alk5, TNFR2, and the adhesion molecules VCAM-1 and ICAM-1 were more frequently detected and at higher levels in normal kidney endothelium as compared to tumor endothelium from intermediate and large tumors." (PMID 22235379, 2011). "We found that lower levels of CD3ε, CD25, CD68, and ICAM-1 mRNA in BCC tumor biopsies at baseline predicted subsequent BCCs." (PMID 21980389, 2011). "Increased expression of ICAM-1, the ligand for lymphocyte function-associated antigen-1 (LFA-1) on both T- and B-lymphocytes, is one effect of IFN-γ that is linked to anti-tumor properties." (PMID 21980389, 2011). "FWGE was shown to upregulate the expression of ICAM-1 on tumor endothelial cells and to synergize these effects of tumor necrosis factor alpha." (PMID 21892933, 2011). "In both cell lines expression level of CD54 (ICAM-1) was up-regulated, which is consistent with cytokines effect on tumor cells." (PMID 21935360, 2011). "Like overexpression of MHC class I protein, the decreased expression of ICAM-1 protein on the endothelial cells of solid tumor vessels impairs access of the immune system to the tumor." (PMID 21892933, 2011). "Soluble MUC1 inhibits adhesion of MUC1-expressing cells to ICAM-1 suggesting an immunosupressive role for the MUC1 shed into the tumor microenvironment and the high levels of circulating mucin often found in advanced stage disease." (PMID 24212946, 2011). "Reduced ICAM-1 expression impairs leukocyte migration through the vessel membrane and thereby inhibits tumor leukocyte infiltration." (PMID 21892933, 2011). "In present study, we analyze the association between the polymorphisms at exon 4 (G241R) and exon 6 (E469K) of ICAM-1 and CRC susceptibility and in vivo differences in ICAM-1 level and differentiation in tumor tissues of patients with CRC." (PMID 19822019, 2009). "This correlated with induction by the tumour cells of ICAM-1 expression on the surface of HMVEC, which is an essential adhesion molecule for surface attachment and transcellular migration of PMN through vascular endothelium." (PMID 20169105, 2009). "Yet the study suggests that ICAM-1 enhances tumor cell attachment to the extracellular matrix by promoting motility in the context of remodeling, and appears to be acting as a morphogen." (PMID 19822019, 2009).
tumor (continued). "Meanwhile, ICAM-1 level was higher in the tumor tissues of individuals with KK genotype than that of the KE+EE genotypes (P < 0.05)." (PMID 19822019, 2009). "The resultant IFN-γ production at the tumor site should specifically increase levels of class I and class II HLA as well as ICAM-1 expression on the tumor cells." (PMID 19497133, 2009). "The distribution of K469E genotypes and allele frequencies in exon 6 of the ICAM-1 was significantly different between CRC patients and controls, and between patients with well differentiation and poor differentiation of tumor tissues." (PMID 19822019, 2009). "KK genotype patients showed an increase in the expression of ICAM-1 protein in tumor tissues relative to the matched normal tissues (P < 0.05)." (PMID 19822019, 2009). "The previous study has showed that expression level of ICAM-1 is high in well differentiated tumor cells and low levels in poorly differentiated cells, and demonstrated a mechanism whereby ICAM-1 expression promotes CRC differentiation and retard metastasis." (PMID 19822019, 2009). "Instead, the tumor cells express ICAM-1 and adhere to neutrophil granulocytes, which then act as a linker connecting the tumor cells to the endothelium and thereby enable firm adhesion." (PMID 19055814, 2008). "We studied the expression of target genes encoding ICAM-1, PAI-1, MCP-1, and p16 to determine the potential roles of ETS-1 and ETS-2 in the development of this tumor." (PMID 18958307, 2008). "The tumor cells lack β2-integrins, which are the ligand for the intercellular adhesion molecule (ICAM)-1 on the endothelium." (PMID 19055814, 2008). "The introduction of heparin to mesothelial-Tumor cells interaction has successfully blocked adhesion by down-regulating ICAM-1 expression." (PMID 19662219, 2007). "We have shown that bi-directional signaling between mesothelial and tumor cells is an important factor in generating cancer invasion and that ICAM-1/CD43 interaction is vital to this phenomenon." (PMID 19662219, 2007). "ICAM-1 has been shown to initiate malignant invasion in a number of malignancies via its interaction with apical MUC-1 on circulating tumor cells and this interaction can be enhanced by tumor cytokine activities." (PMID 19662219, 2007). "ICAM-1 is known to be down-regulated by tumor derived angiogenic factors in order to inhibit leukocyte infiltration and to escape from anti-tumor immune surveillance." (PMID 17147824, 2006). "Decreased expression of ICAM-1 was observed in 12 out of 34 (35%) tumour specimens and de novo expression of HLA-DR (HLA class II) by carcinoma cells in 13 out of 34 (38%) cases." (PMID 9328140, 1997). "Consistent with the in vitro data, tumour endothelia were strongly stained for ICAM-1 compared with autologous normal tissue endothelia." (PMID 9374368, 1997). "ICAM-1 downregulation may reflect a reduced adhesion potential, which could impair tumor cell migration and metastatic spread." (PMID 41596621, 2026). "Indeed, GO treatment resulted in the upregulation of several miRNA-21 responsive genes involved in inflammation and tumor progression including IL-8, ICAM-1, TIMP-2, and NF-κB." (PMID 41596621, 2026). "In early-stage MF, we observed gene expression differences in cells of both the stroma and the immune system, with keratinocytes exhibiting increased interferon response and proliferation (STAT1, ICAM1, HLA-DRA, GJB2), while fibroblasts displayed tumour-associated programs (CXCL2, TNFAIP6, CEBPD)." (PMID 41888970, 2026). "Immunohistochemistry analysis showed SIP‐SII downregulated the expression of intercellular adhesion molecule 1 (ICAM‐1) and basic fibroblast growth factor (bFGF) in lung metastasis nodules, suggesting it inhibits tumour adhesion and angiogenesis, as well as cancer cell invasion and migration." (PMID 41546170, 2026).
tumor (continued). "Additionally, our GSEA results revealed an enhanced inflammatory response signature, marked by increased expression of genes associated with Wnt signalling (ICAM1, HIF1A), a known master regulator of inflammation, tumour progression, and metastasis." (PMID 41486154, 2026). "Our research focused on a set of genes involved in inflammation and tumor progression such as interleukin 8 (IL-8), intercellular adhesion molecule 1 (ICAM-1), monocyte chemoattractant protein-1 (MCP-1), metallopeptidase inhibitor 2 (TIMP-2) and the transcription factor NF-kB." (PMID 41596621, 2026). "Compared to naïve HL-60 human promyelocytic leukemia cells, which cannot be engulfed by tumor cells, differentiated HL-60 (dHL-60) neutrophils, which can be engulfed by tumor cells, express several integrin family genes, such as ICAM-1, ITGAM, ITGB2, ITGAX, and ITGAV, at higher levels." (PMID 39941753, 2025). "ICAM1 is a cell surface protein that aids immune cells in identifying and destroying tumor cells." (PMID 40352921, 2025). "In addition, IL‐12‐activated NCR+ ILC3s have been shown to promote tumour rejection, not through cytotoxicity or IFNγ production, but by inducing expression of adhesion molecules like VCAM‐1 and ICAM‐1 on tumour vasculature, enhancing immune cell infiltration." (PMID 40899118, 2025). "The crucial role of ICAM-1 in limiting tumor progression was reported by several studies." (PMID 40071851, 2025). "As the tumor cells express ICAM1, CD58, and CD80, all of which could contribute to TcE-independent adhesion, we used human serum IgGs as a negative control for TcE-specific effects." (PMID 40445758, 2025). "Clinical precedents involving ICAM1‐targeted CAR‐T cells and oncolytic viruses have also demonstrated favorable safety, supporting the feasibility of ICAM1 as a therapeutic target, particularly when paired with tumor‐localized activation strategies such as NIR‐pyroptosis." (PMID 40539828, 2025). "These agents may also inhibit neutrophil migration—an important mechanism given that tumour cells can exploit neutrophil adhesion, mediated by intercellular adhesion molecule-1 (ICAM-1), to traverse the endothelium more easily." (PMID 40507646, 2025). "Furthermore, administration of WT EVs rescued impaired HuR-knockout tumor growth, increased endothelial cell abundance, and decreased endothelial cell ICAM-1 expression." (PMID 40814996, 2025). "Next, we leveraged the Ivy-GBM cohort to integrate the transcriptional signatures of MES-like tumor cells, ICAM1+ MDMs, GPNMB+ MDMs, COL6A3+ TAFs, endothelial cells, and NK/T cells with distinct histological regions of GBM tissues, estimating the relative proportions of each cell cluster." (PMID 41174767, 2025). "Additionally, NETs and intact neutrophils can capture tumor cells through Mac-1/ICAM-1 interactions, enhancing tumor cell adhesion and promoting metastasis." (PMID 39759427, 2025). "Additionally, thalidomide has promising therapeutic potential in tumor treatment, as shown by its ability to inhibit lung cancer cell invasion and metastasis, which involves the suppression of NF-κB-mediated ICAM-1 expression." (PMID 40562870, 2025). "Furthermore, in IL-6-deficient mice, HT increased ICAM-1 expression on tumor vessels and induce CD8+ T-cell infiltration into the tumor." (PMID 40092992, 2025). "In addition, we found that enhancing ICAM1 signaling in these endothelial cells is key to attracting more immune cells to the tumor sites." (PMID 40107247, 2025). "Moreover, intercellular adhesion molecule 1 (ICAM-1), a member of the immunoglobulin superfamily, facilitates the adhesion of tumor cells to endothelial cells, promoting tumor metastasis." (PMID 40297806, 2025). "Once the tumor volume reached ≈200 mm3, intravenous injection of 100 μg ICAM1‐ICG was administered." (PMID 40539828, 2025).